MIR376B (microRNA 376b)
Synonyms: hsa-mir-376b; MIRN376B; mir-376b
Gene: MicroRNA gene on chromosome 14 (101,040,436 to 101,040,535, forward strand). Ensembl gene ENSG00000283556.
Gene Ontology:
Biological process: miRNA-mediated post-transcriptional gene silencing
Cellular component: RISC complex
Diseases named in the same sentence as MIR376B in open-access papers:
MIR376B is named in the same sentence as 8 diseases in open-access papers, as found by Europe PMC text mining. Sharing a sentence is not in itself a finding about the gene and the disease.
MIR376B shares sentences with these, for which no sentence is quoted: acute myeloid leukemia (1 paper); breast carcinoma (1); esophageal cancer (1); glioblastoma (1); melanoma (1); pancreatic carcinomas (1); renal cell carcinoma (1); Uterine leiomyoma (1).